DDX12P (DEAD/H-box helicase 12, pseudogene)
Description:
DNA helicase involved in cellular proliferation. Probably required for maintaining the chromosome segregation (By similarity).
Synonyms: CHLR2; formerly DDX12
Gene: Transcribed unprocessed pseudogene on chromosome 12 (9,418,670 to 9,448,229, reverse strand). Ensembl gene ENSG00000214826.
Subcellular location: Nucleus
Diseases named in the same sentence as DDX12P in open-access papers:
DDX12P is named in the same sentence as 2 diseases in open-access papers, as found by Europe PMC text mining. Sharing a sentence is not in itself a finding about the gene and the disease. The quoted sentences say what the papers report.
tumor (4 papers, 2020 to 2024). "The composite plot indicated that SDHAP1, SDHAP3, DDX12P, CLUHP3, and RRN3P3 demonstrated high expressions in the low-risk subtype, which were categorized as tumor-suppressor pseudogenes in our study." (PMID 36438489, 2022). "Furthermore, expression patterns of DDX12P were correlated with anti-tumor response and may regulate immune-involved genes through miRNA targeting." (PMID 39450169, 2024). "Except for GVINP1 and NCF1C, the expression of the other 5 prognosis-related DE pseudogenes (DDX12P, FER1L4, NSUN5P2, PLEKHA8P1 and RP9P) were higher in tumor tissues than in cutting edge normal tissues, which was totally consistent with the results of TCGA samples." (PMID 36272991, 2022). "Compared to HPV negative, patients with HPV positive had significantly higher expressions of oncogene pseudogenes (SDHAP1, SDHAP3, DDX12P, CLUHP3, and RRN3P3), but there was no prominent difference in the expressions of tumor-suppressor pseudogenes (PDIA3P1, LDHAP4, LDHAP7, EEF1A1P6, and EEF1A1P11)." (PMID 36438489, 2022).
cancer (1 paper, 2022). A tumor composed of atypical neoplastic, often pleomorphic cells that invade other tissues. "However, for the remaining pseudogenes (DDX12P, NCF1C, RP9P, and YWHAZP4), there were no reports on their biological functions in cancers." (PMID 36272991, 2022).